ALPL (alkaline phosphatase, biomineralization associated)
Description:
Alkaline phosphatase that metabolizes various phosphate compounds and plays a key role in skeletal mineralization and adaptive thermogenesis. Has broad substrate specificity and can hydrolyze a considerable variety of compounds: however, only a few substrates, such as diphosphate (inorganic pyrophosphate; PPi), pyridoxal 5'-phosphate (PLP) and N-phosphocreatine are natural substrates. Plays an essential role in skeletal and dental mineralization via its ability to hydrolyze extracellular diphosphate, a potent mineralization inhibitor, to phosphate: it thereby promotes hydroxyapatite crystal formation and increases inorganic phosphate concentration. Acts in a non-redundant manner with PHOSPHO1 in skeletal mineralization: while PHOSPHO1 mediates the initiation of hydroxyapatite crystallization in the matrix vesicles (MVs), ALPL/TNAP catalyzes the spread of hydroxyapatite crystallization in the extracellular matrix (By similarity). Also promotes dephosphorylation of osteopontin (SSP1), an inhibitor of hydroxyapatite crystallization in its phosphorylated state; it is however unclear whether ALPL/TNAP mediates SSP1 dephosphorylation via a direct or indirect manner (By similarity). Catalyzes dephosphorylation of PLP to pyridoxal (PL), the transportable form of vitamin B6, in order to provide a sufficient amount of PLP in the brain, an essential cofactor for enzymes catalyzing the synthesis of diverse neurotransmitters. Additionally, also able to mediate ATP degradation in a stepwise manner to adenosine, thereby regulating the availability of ligands for purinergic receptors (By similarity). Also capable of dephosphorylating microbial products, such as lipopolysaccharides (LPS) as well as other phosphorylated small-molecules, such as poly-inosine:cytosine (poly I:C). Acts as a key regulator of adaptive thermogenesis as part of the futile creatine cycle: localizes to the mitochondria of thermogenic fat cells and acts by mediating hydrolysis of N-phosphocreatine to initiate a futile cycle of creatine dephosphorylation and phosphorylation (By similarity). During the futile creatine cycle, creatine and N-phosphocreatine are in a futile cycle, which dissipates the high energy charge of N-phosphocreatine as heat without performing any mechanical or chemical work (By similarity).
Synonyms: AP-TNAP; TNS-ALP; TNSALP; TNALP; TNAP; APTNAP; HOPS; HPPA; HPPC; HPPI; HPPO
Tractability: Small molecule: a high-quality ligand is known; it belongs to a druggable protein family. Antibody: UniProt places it where antibodies can reach, with high confidence; its Gene Ontology location is reachable by antibodies, with high confidence; UniProt predicts a signal peptide or a membrane-spanning region. PROTAC: its protein half-life has been measured; a small molecule that binds it is known.
Target class: Enzyme; Phosphatase
Chemical probes: ML038, ML039, ML087, ML088, TNAP-IN-1
Gene: Protein-coding gene on chromosome 1 (21,509,397 to 21,578,410, forward strand). Ensembl gene ENSG00000162551.
Subcellular location: Cell membrane; Extracellular vesicle membrane; Mitochondrion membrane; Mitochondrion intermembrane space
Subcellular location (Human Protein Atlas): Cytosol
Pathways (Reactome):
Metabolism of proteins: Post-translational modification: synthesis of GPI-anchored proteins
Gene Ontology:
Molecular function: alkaline phosphatase activity; calcium ion binding; inorganic diphosphate phosphatase activity; phosphocholine phosphatase activity; phosphoethanolamine phosphatase activity; pyridoxal phosphatase activity; pyrophosphatase activity; ADP phosphatase activity; ATP hydrolysis activity; phosphoamidase activity; 5'-nucleotidase activity; phosphatase activity
Biological process: calcium ion homeostasis; osteoblast differentiation; response to vitamin D; bone mineralization; positive regulation of cold-induced thermogenesis; skeletal system development; cementum mineralization; futile creatine cycle; inhibition of non-skeletal tissue mineralization; phosphate ion homeostasis; pyridoxal phosphate metabolic process; response to glucocorticoid; response to insulin; response to lipopolysaccharide; response to macrophage colony-stimulating factor; response to sodium phosphate; response to vitamin B6
Cellular component: extracellular exosome; membrane; plasma membrane; extracellular region; mitochondrial intermembrane space; mitochondrial membrane; extracellular matrix; extracellular membrane-bounded organelle
Genetic constraint (gnomAD): Loss-of-function variants: 42 observed, 55.07 expected, observed/expected ratio (o/e) 0.76, 90% interval 0.6 to 0.99. The upper end of that interval is the gene's LOEUF score, 0.99, which puts it in group 4 of 6, group 1 being the genes least tolerant of losing a copy. Missense variants: 589 observed, 730.44 expected, observed/expected ratio (o/e) 0.81, 90% interval 0.75 to 0.86. Synonymous variants: 279 observed, 304 expected, observed/expected ratio (o/e) 0.92, 90% interval 0.83 to 1.01.
Gene-disease validity (ClinGen):
ClinGen rates the evidence that ALPL causes each of these diseases.
ALPL-related autosomal dominant hypophosphatasia (autosomal dominant): Definitive. Any hypophosphatasia in which the cause of the disease is a variant with a dominant negative effect or haploinsufficiency in the ALPL gene.
ALPL-related autosomal recessive hypophosphatasia (autosomal recessive): Definitive. Any hypophosphatasia in which the cause of the disease is an autosomal recessive loss-of-function in the ALPL gene.
Homologues: Orthologues: chimpanzee ALPL (99% identical), macaque ALPL (97% identical), pig ALPL (91% identical), rat Alpl (91% identical), guinea pig ALPL (91% identical), dog ALPL (90% identical), mouse Alpl (90% identical), rabbit ALPL (83% identical), tropical clawed frog alpl (73% identical), zebrafish alpl (72% identical), Drosophila melanogaster Alp6 (41% identical), Drosophila melanogaster phu (41% identical), and 11 more. Paralogues in human: ALPI (55% identical), ALPG (54% identical), ALPP (53% identical).
Diseases named in the same sentence as ALPL in open-access papers:
ALPL is named in the same sentence as 175 diseases in open-access papers, as found by Europe PMC text mining. Sharing a sentence is not in itself a finding about the gene and the disease. The quoted sentences say what the papers report.
hypophosphatasia (234 papers, 2006 to 2026). Hypophosphatasia (HPP) is a rare heritable metabolic disorder characterized by defective mineralization of bone and/or teeth in the presence of reduced activity of unfractionated serum alkaline phosphatase (ALP). "For hypophosphatasia caused by ALPL genetic variants, comprehensive treatment typically includes calcium supplementation, orthopedic correction, and supportive care." (PMID 40703321, 2025). "Association renal impairment with c.1559del of ALPL in adults with hypophosphatasia is overlooked for a long time." (PMID 39926094, 2025). "Genetic testing was performed, showing a heterozygous mutation in the ALPL gene, with the pathogenic variant (p.Ala116Thr) consistent with hypophosphatasia." (PMID 40255721, 2025). "Genetics confirmed a homozygous pathogenic variant c.783C>G p.(Tyr261*) in ENPP1 and a heterozygous pathogenic ALPL variant consistent with hypophosphatasia." (PMID 41445557, 2025). "This study presents a case report of an 11-year-old boy with hypophosphatasia due to compound heterozygous ALPL gene genetic variants, focusing on the treatment effects of comprehensive approaches for this rare genetic disorder." (PMID 40703321, 2025). "Hypophosphatasia is caused by mono- or biallelic pathogenic variants in the ALPL gene encoding the TNSALP protein." (PMID 41445557, 2025). "Here we report a Chinese infant with hypophosphatasia (HPP) carrying alkaline phosphatase (ALPL) gene mutations." (PMID 41350270, 2025). "Hypophosphatasia is a rare genetic condition resulting from various mutations of the ALPL gene, which leads to defective TNSALP enzymes." (PMID 40255721, 2025). "This study explores the impact of ALPL gene genetic variants on hypophosphatasia and chest wall deformities and evaluates the benefits of corrective surgery in improving respiratory function and quality of life in children." (PMID 40703321, 2025). "Hypophosphatasia results from pathogenic variants in the ALPL gene, which disrupt normal skeletal metabolism." (PMID 40703321, 2025). "Hypophosphatasia (HPP) is a metabolic disorder caused by a loss of function mutation in the ALPL gene, leading to reduced tissue activity of alkaline phosphatase (ALP)." (PMID 41065917, 2025). "Case 1 and 2 were also found to have a heterozygous pathogenic ALPL variant consistent with hypophosphatasia." (PMID 41445557, 2025). "Loss of function of the ALPL gene results in hypophosphatasia (HPP), a hereditary disease with high incidence." (PMID 38609899, 2024). "The ALPL gene is known to cause autosomal recessive infantile hypophosphatasia (OMIM, #241500) and dominant or recessive adult odontohypophosphatasia (OMIM, #146300)." (PMID 38586466, 2024). "Hypophosphatasia (HPP) is a genetic disease caused by loss-of-function mutations in ALPL located in chromosome 1q36.12." (PMID 36820543, 2023). "The severity of hypophosphatasia generally reflects the inheritance pattern of ALPL mutations, with autosomal recessive inheritance more common in perinatal and infantile cases." (PMID 33990852, 2022). "Low serum alkaline phosphatase levels are the hallmark of hypophosphatasia, a disorder due to pathogenic variants of the ALPL gene." (PMID 36072928, 2022). "Hypophosphatasia (HPP) is a heritable disorder caused by a genetic sequence variation in the ALPL gene affecting bone mineralization." (PMID 36447830, 2022). "Hypophosphatasia (HPP) is a rare genetic disorder caused by a mutation in the alkaline phosphatase liver/bone/kidney type (ALPL) gene." (PMID 35453912, 2022). "It is unclear if those patients have hypophosphatasia due to an undetected ALPL variant (such as variants in regulatory, intronic region or even epimutations), in other genes not yet associated with HPP, or have a different disorder." (PMID 36072928, 2022). "Mutation in the ALPL gene can lead to persistent low ALP activity resulting in the rare disease Hypophosphatasia (HPP) that is characterized by disturbed bone and dental mineralization." (PMID 34711245, 2021).
hypophosphatasia (continued). "Pathogenic variants in ALPL cause hypophosphatasia characterized by defective mineralization of bone and/or teeth in the presence of low activity of serum and bone alkaline phosphatase (ALP)." (PMID 33777089, 2021). "Hypophosphatasia is a rare disorder induced by a mutation in the ALPL gene resulting in a diminished activity of the enzyme in target tissues." (PMID 34198561, 2021). "A common manifestation of loss of TNAP activity or mutations to ALPL gene causes a systemic bone disease called hypophosphatasia (HPP) resulting in hypomineralization of hard skeletal tissues including bone and teeth." (PMID 34827562, 2021). "Pathogenic mutation within the ALPL gene causes a decrease of ALP activity resulting in the disease Hypophosphatasia (HPP) that causes decreased bone and dental mineralization and is characterized by neurological, musculoskeletal and renal manifestation." (PMID 34711245, 2021). "A previously unidentified heterozygous variant located in exon 11 of the ALPL gene -c.1292T>A- is described as a cause of hypophosphatasia." (PMID 30929401, 2020). "The lack of awareness of patient risk factors, failure to obtain adequate family history, was discussed by clinical experience in prenatal testing of hypophosphatasia with a novel variant in the ALPL gene identified in the index case of the family." (PMID 32983484, 2020). "Hypophosphatasia derives from any mutation in the ALPL gene located on chromosome 1p36.1 that causes decreased TNSALP activity and increased levels of its substrates." (PMID 30864637, 2019). "In humans, recessive and dominant ALPL mutations cause hypophosphatasia (HPP), a metabolic bone disease with highly heterogeneous clinical manifestations, ranging from lethal perinatal hypomineralization to a relatively mild dental disease." (PMID 30700765, 2019). "Studies of hypophosphatasia, a rare inborn-error-of-metabolism, caused by missense mutations within the TNALP gene (ALPL), have provided evidence for an important role for ALP in the development and mineralization of bone." (PMID 28303318, 2017). "Hypophosphatasia is a rare inherited disorder of bone and mineral metabolism caused by a number of loss-of-function mutations in the ALPL gene." (PMID 27086862, 2016). "In humans, mutations in ALPL genes cause hypophosphatasia, a rare inherited disorder characterized by deficiency of serum and bone alkaline phosphatase activity, resulting in the defective bone and tooth mineralization." (PMID 27458382, 2016). "Herein, we report the case of an infantile hypophosphatasia patient who presented with pyridoxine-responsive seizures and a novel homozygous mutation in the ALPL gene was detected." (PMID 27086862, 2016). "Hypomorphic mutations in the ALPL gene encoding TNAP lead to accumulation of PPi in the extracellular matrix causing a heritable form of rickets in children or osteomalacia in adults known as hypophosphatasia." (PMID 25709758, 2015). "Hypomorphic mutations in ALPL, the gene encoding human TNAP (Alpl in mice) lead to hypophosphatasia, a heritable form of rickets or osteomalacia." (PMID 25775211, 2015). "In humans, over 261 different mutations in ALPL have been linked to hypophosphatasia and skeletal abnormalities, of which 75% are missense mutations." (PMID 23091474, 2012). "The best studied biological function of Alps is the role of mammalian Alpl in osteogenesis by promoting bone mineralization, as demonstrated by the hypophosphatasia that results from ALPL deficiency in humans and mice." (PMID 23091474, 2012). "Mutations in the TNAP gene (ALPL) leads to hypophosphatasia, an inborn error of metabolism that features rickets or osteomalacia as a result of accumulated levels of extracellular PPi, resulting from suboptimal TNAP’s pyrophosphatase activity." (PMID 20657462, 2010).
hypophosphatasia (continued). "These defects recall the occurrence of seizures in patients with mutations in the ALPL gene, suffering from severe hypophosphatasia." (PMID 19652718, 2009). "Among the 361 samples from unrelated patients sent to our laboratory to explore the possible diagnosis of hypophosphatasia by molecular analysis of the ALPL gene, 241 were found to carry at least one single mutation." (PMID 19500388, 2009). "The search terms were (hypophosphatasia), (ALPL), and (polymorphism or gene or allele or SNP)." (PMID 41158885, 2025). "In summary, this study effectively demonstrates the pivotal role of ALPL genetic variants in developing hypophosphatasia and highlights the significance of corrective surgery in ameliorating chest wall deformities and respiratory function through an in-depth analysis of a hypophosphatasia patient." (PMID 40703321, 2025). "Hypophosphatasia is a rare genetic condition caused by various mutations of the ALPL gene." (PMID 40255721, 2025). "Moreover, in a cohort of patients with persistent biological hypophosphatasia, those with a genetic variant of the ALPL gene reported statistically more musculoskeletal pain than those with negative genetic tests." (PMID 38673536, 2024). "The presence of a pathogenic variant of the ALPL gene (major criterion), chronic musculoskeletal pain, early atraumatic loss of teeth, and chondrocalcinosis (three minor criteria) allowed us to make a final diagnosis of hypophosphatasia." (PMID 38673536, 2024). "Hypophosphatasia (HPP) is a rare genetic metabolic disorder with mutations in the ALPL gene, which, in addition to causing problems with bone and tooth mineralization, tends to produce problems associated with the central nervous system (CNS), such as seizures, anxiety and depression." (PMID 37265554, 2023). "Promoting an increase in ALP is predicted to ensure the formation of a mechanically competent, mineralised bone matrix; individuals with missense mutations in the ALPL gene have hypophosphatasia, a condition characterised by poorly mineralised bone, sharing similarities with childhood rickets." (PMID 37509149, 2023). "Hypophosphatasia (HPP) is a rare genetic disease caused by inactivating variants of the ALPL gene." (PMID 37600704, 2023). "On the other hand, adults with persistent hypophosphatasemia frequently harbor ALPL mutations and may fall within the spectrum of the adult form of hypophosphatasia." (PMID 34884378, 2021). "The product of ALPL is a membrane bound glycosylated enzyme that broadly participating in phosphatase activity and alkaline phosphatase activity, therefore, the alteration of ALPL is found to be associated with hypophosphatasia and prostate cancer bone metastasis." (PMID 33807688, 2021). "Loss-of-function mutations in ALPL may cause hypophosphatasia (HPP), a rare inherited skeletal dysplasia." (PMID 34394176, 2021). "The cause of hypophosphatasia is loss-of-function or dominant-negative mutations in ALPL." (PMID 33138854, 2020). "Furthermore, ALPL gene mutations were found in patients with hypophosphatasia, characterized by elevated urinary PPi excretion." (PMID 31754202, 2019). "However, it remains labour intensive and is typically reserved for disorders with low genetic heterogeneity (e.g. single‐ or pauci‐gene disorders), an example being hypophosphatasia caused only by TNSALP/ALPL mutations." (PMID 30357886, 2019). "All patients with hypophosphatasia carry one or two mutations involving ALPL." (PMID 30864637, 2019). "Hypophosphatasia is a rare, inborn-error-of-metabolism characterized by defective mineralization of bone and/or teeth caused by loss-of-function mutations in the gene encoding TNAP (ALPL in humans and Akp2 or Alpl in mice)." (PMID 29551976, 2018).